ROPN1B (rhophilin associated tail protein 1B)
Description:
Important for male fertility. With ROPN1L, involved in fibrous sheath integrity and sperm motility, plays a role in PKA-dependent signaling processes required for spermatozoa capacitation.
Tractability: PROTAC: UniProt records ubiquitination sites on it.
Gene: Protein-coding gene on chromosome 3 (125,969,160 to 125,983,454, forward strand). Ensembl gene ENSG00000114547.
Subcellular location: Cell projection, cilium, flagellum
Subcellular location (Human Protein Atlas): Principal piece
Gene Ontology:
Molecular function: protein binding; protein heterodimerization activity; signaling receptor complex adaptor activity
Biological process: acrosome reaction; cell-cell adhesion; cilium organization; cytoskeleton-dependent cytokinesis; flagellated sperm motility; fusion of sperm to egg plasma membrane involved in single fertilization; protein localization to cilium; Rho protein signal transduction; sperm capacitation; spermatogenesis
Cellular component: cytoplasm; motile cilium
Genetic constraint (gnomAD): Loss-of-function variants: 11 observed, 17.61 expected, observed/expected ratio (o/e) 0.62, 90% interval 0.39 to 1.03. The upper end of that interval is the gene's LOEUF score, 1.03, which puts it in group 4 of 6, group 1 being the genes least tolerant of losing a copy. Missense variants: 150 observed, 175.68 expected, observed/expected ratio (o/e) 0.85, 90% interval 0.75 to 0.98. Synonymous variants: 55 observed, 74.03 expected, observed/expected ratio (o/e) 0.74, 90% interval 0.6 to 0.93.
Homologues: Orthologues: chimpanzee ROPN1B (98% identical), macaque ROPN1B (97% identical), macaque ROPN1 (92% identical), dog ROPN1 (87% identical), rat Ropn1 (85% identical), mouse Ropn1 (84% identical). Paralogues in human: ROPN1 (96% identical), ROPN1L (39% identical).
Diseases named in the same sentence as ROPN1B in open-access papers:
ROPN1B is named in the same sentence as 6 diseases in open-access papers, as found by Europe PMC text mining. Sharing a sentence is not in itself a finding about the gene and the disease. The quoted sentences say what the papers report.
breast carcinoma (1 paper, 2025). "Subsequently, we further narrowed down the eight candidate genes (TRIM47, SPHK1, RGMA, ROPN1B, LARP6, ROPN1, NPM2 and LPL) that are shared in TNBC compared to ER+ and HER2+ breast cancer subtypes in cancer cells." (PMID 40635123, 2025).
melanoma (1 paper, 2021). A malignant, usually aggressive tumor composed of atypical, neoplastic melanocytes. "To explore the immunogenic potential of ROPN1A and ROPN1B, we screened sera or plasma from 104 melanoma patients." (PMID 33918976, 2021). "By multispectral immunohistochemistry, 88.5% of melanoma patients tested (n = 54/61) showed ROPN1B expression in at least 1 of 2/3 tumour cores in tissue microarrays." (PMID 33918976, 2021). "Antibody responses against ROPN1A and ROPN1B were detected in 71.2% of melanoma patients tested (n = 74/104), with increased reactivity seen with more advanced disease stages." (PMID 33918976, 2021). "We tested the gene expression levels of ROPN1 and ROPN1B (96% sequence homology with ROPN1) in a panel of melanoma cell lines generated in-house." (PMID 33918976, 2021). "When investigating melanoma TMAs, 88.5% of patient tumours expressed ROPN1B, a much larger proportion compared to NY-ESO-1 (16.4%)." (PMID 33918976, 2021). "Similarly, gene expression of ROPN1 and ROPN1B was also commonly detected in a melanoma patient cohort accessed via the TCGA (ROPN1: 98.9%, ROPN1B: 98.7% vs. CTAG1B: 68.2%)." (PMID 33918976, 2021). "The expression of differentiation antigens that are commonly present and have been previously used as immunological targets in melanoma, namely, TYR (tyrosinase) and MLANA (Melan-A/MART1), were compared with CTAG1A and ROPN1 or ROPN1B in our panel of melanoma cell lines." (PMID 33918976, 2021). "We further investigated ROPN1, ROPN1B and CTAG1B gene expression across different stages of disease and genders in melanoma." (PMID 33918976, 2021). "In this study, gene-expression profiling of a large panel of early-passage melanoma cell lines identified ROPN1 and ROPN1B as being highly expressed in melanoma tumour samples (ROPN1: 81.8%, ROPN1B: 83.6%), more so than CTAG1 (36.4%)." (PMID 33918976, 2021). "Nonetheless, expression was more predominant in advanced disease (ROPN1B: chi-square p-value = 0.003; NY-ESO-1: chi-square p-value = 0.009), with evidence of more abundant melanoma cell expression in tumour cores, in contrast to sparse, dispersed cells commonly identified in early-stage disease." (PMID 33918976, 2021). "We assessed expression of ROPN1B, NY-ESO-1 (single protein from CTAG1A or CTAG1B genes), MLANA and SOX10 (used here as a melanoma tumour marker) at the protein level by multispectral immunohistochemistry on melanoma tissue microarrays (TMAs) comprising two or three cores from 61 patient tumours." (PMID 33918976, 2021). "We therefore hypothesised that this may also be the case in melanoma and aimed to investigate the expression and immunogenicity of ROPN1 and ROPN1B." (PMID 33918976, 2021). "We further evaluated the gene expression levels of ROPN1, ROPN1B, CTAG1B (identical gene copy to CTAG1A for which no gene expression data is available), TYR and MLANA in 472 additional melanoma samples using data accessible via The Cancer Genome Atlas (TCGA)." (PMID 33918976, 2021).
metastatic melanoma (1 paper, 2021). A melanoma that has spread from its primary site to another anatomic site. "Here, we show that Ropporin-1 (ROPN1) and 1B (ROPN1B), cancer restricted antigens, are highly expressed and immunogenic, inducing humoral immunity in patients with advanced metastatic melanoma." (PMID 33918976, 2021).
cancer (2 papers, 2021 to 2025). A tumor composed of atypical neoplastic, often pleomorphic cells that invade other tissues. "For these reasons, the potential to achieve increased tumour coverage by targeting NY-ESO-1, ROPN1A and ROPN1B combined makes these immunogenic CTAgs highly compatible for combination in a cancer vaccine with the potential to generate synergistic immune responses to the tumour." (PMID 33918976, 2021). "Thus, ROPN1A and ROPN1B may indeed be viable targets for cancer immunotherapy, alone or in combination with other cancer antigens, and could be combined with additional therapies such as immune checkpoint blockade." (PMID 33918976, 2021).
tumour (1 paper, 2021). "Expression of both ROPN1B and NY-ESO-1 was seen in 9 cases (n = 9/61, 14.8%), where tumour cells within cores showed instances of co-expression or exclusive expression of ROPN1B and/or NY-ESO-1." (PMID 33918976, 2021). "Even in instances of tumours expressing both NY-ESO-1 and ROPN1B (14.8%), the addition of ROPN1B increased the tumour cell coverage substantially." (PMID 33918976, 2021). "Here, we found that both ROPN1A and ROPN1B have favourable features as tumour antigens based on distribution and immunogenicity." (PMID 33918976, 2021). "In patient samples with expression of both ROPN1B and NY-ESO-1, cells with exclusive ROPN1B positivity increased tumour cell coverage by 29.3% on average (range from 9.0% to 73.0%)." (PMID 33918976, 2021). "Moreover, ROPN1B expression was often detected ubiquitously, whereas NY-ESO-1 appeared more scattered and diffuse throughout tumour cores." (PMID 33918976, 2021).
ROPN1B also shares sentences with these, for which no sentence is quoted: Infertility (1 paper).